REN (renin)
Diseases named in the same sentence as REN in open-access papers (continued):
Sharing a sentence is not in itself a finding about the gene and the disease.
Hypertension (continued). "Hypertension therapy in older adults is often suboptimal, in part because of inadequate suppression of the renin–angiotensin–aldosterone system (RAAS)." (PMID 39709293, 2025). "MU exhibited typical clinical manifestations of PA, including hypertension, hyperaldosteronism, low renin levels and strong sodium retention and potassium excretion abilities." (PMID 39946402, 2025). "Clinically, PA manifests through several distinct markers: elevated plasma aldosterone concentration (PAC), suppressed plasma renin activity, hypertension, and a dysregulated sodium and potassium balance." (PMID 40862117, 2025). "Revealed in one study is the potential for preventing hypertension in adults whose mothers consumed a high-fructose diet by administering the renin inhibitor aliskiren to offspring aged 2–4 weeks." (PMID 39911806, 2025). "The incidence of MACE in Taiwanese patients newly diagnosed with hypertension who had at least 1 year follow-up was 6.0% in the fixed-dose combination of renin-angiotensin system inhibitors and thiazide diuretics group." (PMID 41254820, 2025). "The HUA and hypertension were partially inhibited by losartan (an angiotensin II receptor blocker) suggesting involvement of activation of the renin-angiotensin system in developing hypertension." (PMID 39968300, 2025). "Marked activation of the renin–angiotensin–aldosterone system (RAAS) plays an important role in malignant hypertension (MHT) by worsening hypertension and renal function." (PMID 39349898, 2025). "Renin converts angiotensinogen to angiotensin I, and angiotensin-converting enzyme (ACE) metabolizes angiotensin I to angiotensin II, which causes high blood pressure and leads to myocardial hypertrophy and fibrosis." (PMID 41426862, 2025). "Performance of aldosterone-to-renin ratio (ARR) cut-off values for primary aldosteronism detection: primary aldosteronism versus essential hypertension patients using Lumipulse®." (PMID 39999127, 2025). "Because of the role of the renin-angiotensin system in blood pressure regulation, ACE is a strong risk factor for essential hypertension." (PMID 40370871, 2025). "The main manifestations of this condition are high blood pressure, an increased aldosterone serum level, and suppressed circulating renin." (PMID 39859256, 2025). "In general, aldosterone and renin measurements are routinely conducted for screening secondary hypertension at general practitioner offices in Japan." (PMID 38715590, 2024). "At the cellular and molecular levels, hypertension and OA share some common molecular pathways, such as the renin-angiotensin system, endothelin system and Wnt-β-catenin signalling pathway." (PMID 38997710, 2024). "It should be suspected in patients with a family history of early-onset hypertension, hypokalemia, suppressed plasma renin activity or elevated aldosterone-to-renin ratio." (PMID 38700500, 2024). "Low-renin hypertension (LRH), commonly defined as a plasma renin activity of <1 ng/mL/hour, is present in 30% of patients with hypertension." (PMID 39857638, 2024). "ACE is a hydrolase of N = 598 residues acting in the blood pressure-regulating renin-angiotensin system and is a major drug target against hypertension and heart failure." (PMID 39585988, 2024). "Patient characteristics were similar, aside from a lower aldosterone concentration compared to patients with normal-renin hypertension and PA." (PMID 38957654, 2024). "Patients with hypertension can be divided into low-, normal-, or high-renin hypertension based on their serum renin levels." (PMID 39184766, 2024). "The male group had significantly higher rates of hypertension (54.1% vs. 16.7%, p = 0.043) and renin-angiotensin system inhibitor (RASi) use (32.4% vs. 0%, p = 0.024) than the female group." (PMID 39020443, 2024). "Hypertension development is multifactorial in humans, with the renin–angiotensin–aldosterone system playing a substantial role." (PMID 38554187, 2024).
Hypertension (continued). "In summary, GRA is a rare genetic disorder that should be considered in patients presenting with early-onset hypertension, hypokalemia, metabolic alkalosis, and low renin levels." (PMID 38691164, 2024). "Relevant examinations revealed low blood potassium, low cortisol, high adrenocorticotropic hormone, low renin, and low aldosterone levels in the patients, with Case 2 also having significant hypertension." (PMID 38872965, 2024). "Plasma renin and aldosterone levels should be checked in patients with hypokalemia and hypertension." (PMID 39840167, 2024). "In focusing on mineralocorticoid receptor antagonists as the appropriate treatment forlow-renin hypertension, they ignore the important existence of 2 streams of low-reninhypertension: low renin/high aldosterone and low renin/low aldosterone." (PMID 39281004, 2024). "Direct renin inhibitors, like aliskiren, offer a novel approach to managing hypertension and HF by directly inhibiting the enzyme renin." (PMID 39273041, 2024). "In this regard, the renin–angiotensin system, which is dysregulated in both hypertension and obesity, is a prime therapeutic target." (PMID 39769086, 2024). "Patients with low-renin hypertension were older and more likely to be female compared to normal-renin hypertension (57.1 ± 12.8 years vs 51.8 ± 14.0 years, P < .05 and 68.1% vs 49.3%, P < .05, respectively) but similar to PA (53.5 ± 11.5 years and 55.3%)." (PMID 38957654, 2024). "Genetic modifications in the renin-angiotensin aldosterone system (RAAS) have been suggested to play a key role in the pathophysiology of hypertension." (PMID 39666621, 2024). "Activation of the renin–angiotensin–aldosterone system (RAAS) plays an important pathophysiological role in hypertension." (PMID 39125667, 2024). "Estrogen protects against hypertension by reducing sympathetic activity, enhancing baroreflex sensitivity, lowering oxidative stress, increasing nitric oxide production, and balancing the renin–angiotensin–aldosterone system." (PMID 39727950, 2024). "Patients with decreased eGFR often suffer from increased sympathetic and renin‐angiotensin system (RAS) overactivation or hypertension." (PMID 38726345, 2024). "Nevertheless, plasma renin activity remains important in identifying cases of low-renin hypertension, particularly in monogenic forms." (PMID 39597921, 2024). "Two cases of renin-producing Sertoli cell tumors in female patients have been documented, both presenting with hypertension." (PMID 40071053, 2024). "This can activate the renin-angiotensin system and induce pro-inflammatory cytokines, leading to intraglomerular hypertension, vascular dysfunction, and inflammation, which in turn can contribute to cardiovascular and renal complications." (PMID 38809295, 2024). "Fourthly, while the review emphasizes hepatic AGT as the primary therapeutic target, it provides limited information on other emerging targets within the renin–angiotensin system or alternative pathways contributing to hypertension." (PMID 39852196, 2024). "Autonomic control of hypertension from the Central Nervous System (CNS) is maintained by sympathetic processes, which regulate the systemic renin-angiotensin system (RAS) and inflammation through the hypothalamic-pituitary-adrenal-axis (HPAA)." (PMID 39514592, 2024). "It is recommended that patients with diabetes, hypertension, and albuminuria should be treated with an (renin-angiotensin system) RAS inhibitor, such as an ACEi or ARB, at the highest tolerated dose." (PMID 39337706, 2024). "The renin-angiotensin system (RAS), traditionally associated with hypertension, has emerged as a potential player in these disorders." (PMID 38248795, 2024). "The purpose of this study was to optimize the protease treatment condition to produce PPH with high ACE- and renin-inhibitory activity for possible food therapy of hypertension." (PMID 39000571, 2024).
Hypertension (continued). "Obesity-related hypertension develops due to the overactivation of the sympathetic nervous system, stimulation of the renin-angiotensin-aldosterone system, alterations in adipose-derived cytokines such as leptin, and insulin resistance." (PMID 38373927, 2024). "Epigenetic regulation by histone deacetylases (HDACs) and alterations of the renin–angiotensin system (RAS) are involved in the developmental programming of hypertension." (PMID 39519150, 2024). "It has been demonstrated that miR-181a and miR-663 directly bind renin mRNA, and their levels were markedly decreased in hypertension individuals." (PMID 38605867, 2024). "In children exhibiting low renin hypertension, hypokalemia, and with a family background of severe hypertension diagnosed during youth, refractory hypertension, cerebral vascular accidents, and heart failure causing death, genetic tests should be considered." (PMID 38790513, 2024). "With regards to hypertension, this includes inhibitors of the renin-angiotensin aldosterone system (RAAS), in addition to other therapies like statins and antioxidants." (PMID 38424404, 2024). "The authors suggested that testosterone contributes to the development of hypertension and renal injury in male Dahl salt-sensitive rats fed a high-salt diet, possibly through the upregulation of the intrarenal renin-angiotensin system." (PMID 38846628, 2024). "Presently used synthetic drugs for hypertension management, such as captopril, alacepril, lisinopril, and enalapril, are mostly ACE inhibitors, and aliskiren is the only synthetic renin inhibitor approved by the FDA for managing hypertension." (PMID 39000571, 2024). "Angiotensin II receptor blockers (ARBs) are a group of medications used to treat hypertension by inhibiting the renin–angiotensin system." (PMID 38473793, 2024). "In this study, patients with hypertension and low renin plasma activity showed an impaired vasodilating response to methacholine and nitroprusside." (PMID 38256505, 2024). "The relationship between obesity and hypertension is widely recognized as a result of the interrelated mechanisms induced by obesity, including activation of the sympathetic nervous system, the renin-angiotensin-aldosterone system, and abnormal renal function." (PMID 39600783, 2024). "The renin–angiotensin system (RAS) is well recognized to be dysregulated in both hypertension and obesity and to contribute to the development and pathogenesis of these conditions." (PMID 39769086, 2024). "This condition, characterised by excessive aldosterone secretion, leads to augmented sodium and water reabsorption alongside potassium loss, culminating in distinct clinical hallmarks: elevated aldosterone levels, suppressed renin levels, and hypertension." (PMID 38255973, 2024). "Renin–angiotensin–aldosterone system (RAAS) inhibitors are standard care in patients with hypertension, heart failure or chronic kidney disease (CKD)." (PMID 38612843, 2024). "For patients with severe hypertension, hypokalemia, low renin, low aldosterone, and multi-organ damage, a step-by-step differential diagnosis should be conducted through biochemical tests and imaging studies." (PMID 39931437, 2024). "In fact, it is commonly accepted that there is a continuum between low-renin primary (essential) hypertension and PA and a diagnosis is only obtained in patients who fulfil the criteria suggested for its diagnosis." (PMID 37964158, 2024). "It is widely demonstrated that inhibition of the renin-angiotensin–aldosterone system (RAAS), like Ramipril, has been widely used to reduce proteinuria and to treat hypertension, one of the main causes of renal failure in the elderly patients." (PMID 37450242, 2024). "Patients with 11OHD exhibit high serum levels of 11-deoxycorticosterone, which is known to have mineralocorticoid activity, leading to suppressed renin levels and hypertension as observed in the oldest 11OHD patient (aged 13)." (PMID 39175568, 2024).
Hypertension (continued). "In hypertension, Angiotensin II (Ang II) is produced as a byproduct of the renin-angiotensin system." (PMID 39684449, 2024). "The renin–angiotensin system (RAS) also plays an important role in supporting both hypertension and inflammation." (PMID 39597955, 2024). "Patients with FH present with variable degrees of hypertension, hypokalemia, metabolic alkalosis, suppressed renin, and elevated aldosterone production, typically with onset early in life." (PMID 39803142, 2024). "PA is traditionally characterized by hypertension and hypokalemia resulting from renin-independent hypersecretion of aldosterone by either a nodule or a hyperplastic adrenal cortex in the zona glomerulosa of the adrenal glands." (PMID 39803142, 2024). "However, when the renin-angiotensin-aldosterone system is dysregulated, such as in the case of primary aldosteronism (PA), there is a loss of the negative feedback mechanism, leading to inappropriate MR activation promoting excess sodium and water reabsorption, hypertension and end-organ damage." (PMID 38200100, 2024). "Thus, it has been postulated that the root causes of the development of hypertension in SHR rats may be associated with the over-activation of the RAAS through stimulated renin release from the kidneys and enhanced oxidative stress due to the activity of NADPH oxidase." (PMID 39057713, 2024). "Guidelines for hypertension management commonly recommend combination therapy involving a renin-angiotensin system inhibitor with a calcium channel blocker or combined diuretic." (PMID 38903964, 2024). "If renin-independent aldosterone excess persists, the distal nephron will reabsorb sodium into the body, and potassium will flow out, resulting in hypertension and hypokalemia as the typical PA phenotype." (PMID 39877848, 2024). "Another condition to consider is Liddle syndrome, a rare genetic disorder caused by a mutation that increases the activity of ENaC in the kidneys, resulting in low-renin, low-aldosterone hypertension." (PMID 39498427, 2024). "Adults with hypertension, who are treatment naïve or are receiving up to two antihypertensive agents and have a low direct renin concentration <10 mU/L will be included." (PMID 39026100, 2024). "A possible explanation for the development of new-onset hypertension following SARS-CoV-2 infection includes the disruption of the renin-angiotensin-aldosterone system (RAAS)." (PMID 39099965, 2024). "One study found that normal-weight (BMI 18.5–25) participants with hypertension secrete more catecholamines and renin during exercise than obese (BMI > 30) participants." (PMID 38732147, 2024). "The patient's presentation of hypertension with hypokalemia and metabolic alkalosis, and low plasma renin and serum aldosterone levels suggested the diagnosis of AME or Liddle syndrome." (PMID 39107810, 2024). "These bioactive compounds are acclaimed for their ability to prevent hypertension or regulate blood pressure levels, which are believed to operate via modulating the renin–angiotensin–aldosterone system, inflammation, and oxidative stress." (PMID 39275342, 2024). "They exhibited classic features of metabolic alkalosis, low renin, low aldosterone, hypokalemia, and hypertension." (PMID 39931437, 2024). "Thus, renin-independent aldosterone production can be detected in both normotensive and hypertensive individuals, with its severity correlating with blood pressure elevation, incident hypertension risk, cardiovascular disease, and the effectiveness of MRA therapy." (PMID 39445045, 2024). "Due to the increase in DOC, some patients develop hypertension with low aldosterone and low renin with hypokalemia." (PMID 37486441, 2024). "The Renin-angiotensin-aldosterone system (RAAS) plays a crucial role in the pathogenesis of hypertension, prompting the latest guidelines to recommend angiotensin II receptor blockers (ARBs) as first-line therapy." (PMID 38903964, 2024).
Hypertension (continued). "Currently, aliskiren holds the distinction of being the inaugural renin inhibitor sanctioned for the treatment of hypertension." (PMID 38542273, 2024). "Elevated aldosterone levels cause the synchronous decrease of renin, resulting not only in hypervolemic hypertension but also in an increased aldosterone-to-renin ratio." (PMID 38771379, 2024). "First, proximal renal arterial involvement has the potential to induce systemic hypertension and subsequent secondary hypertensive nephropathy via the renin–angiotensin–aldosterone system." (PMID 39407892, 2024). "Sympathetic activation in hypertension also depends on the interaction with the renin–angiotensin–aldosterone system." (PMID 39457606, 2024). "Dysregulated DNA methylation of renin–angiotensin system genes is involved in the pathogenesis of hypertension and cardiovascular diseases." (PMID 39125667, 2024). "The loss of differentiation in renin-producing cells and the subsequent increase in their population results in elevated levels of plasma renin and the development of hypertension." (PMID 38691164, 2024). "Low-renin hypertension (LRH) is characterized by hypertension accompanied by low serum renin levels." (PMID 39184766, 2024). "This case report presents the clinical findings of a 47-year-old woman with a history of recurrent hypokalemia, headaches, hypertension, and increased plasma renin activity (PRA)." (PMID 38304038, 2024). "The retrospective diagnosis of low-renin hypertension is challenging as many commonly used antihypertensives interfere with direct renin concentration interpretation." (PMID 39026100, 2024). "Hypertension involves the activation of the renin-angiotensin system (RAS) alongside oxidative stress-induced endothelial dysfunction and local inflammation mediated by T cells." (PMID 39877020, 2024). "Within the operation group, characterized by older age, longer hypertension duration, lower blood pressure, higher aldosterone, and lower renin levels, and there were 5 patients with refractory hypertension." (PMID 38965078, 2024). "Second, L-NAME-induced hypertension was previously shown to be a model with low renin–angiotensin II pathway activation." (PMID 38672089, 2024). "The syndrome of apparent mineralocorticoid excess (AME), or pseudo-hyperaldosteronism, is characterized by hypertension with hypokalemia with low plasma renin and serum aldosterone levels." (PMID 39107810, 2024). "The renin–angiotensin–aldosterone system (RAAS) plays a pivotal role in the overall pathophysiology of hypertension." (PMID 39125667, 2024). "These featureswere also observed in our study, which aimed to estimate the prevalence and characteristics oftreatment-naïve people with low-renin hypertension in primary care." (PMID 39281005, 2024). "A recent study has suggested that the elevated resting metabolic rate (RMR) can be normalized by antagonizing the renin‐angiotensin system in obese or overweight patients with hypertension." (PMID 38726345, 2024). "Recent studies have reported the correlation between low renin, markers of increased MR activity, and progressive development of incident hypertension." (PMID 39026100, 2024). "One-third of patients with hypertension have low or suppressed renin, which suggests systemic volume expansion and mineralocorticoid receptor (MR) activation." (PMID 38586159, 2024). "AGEs work synergistically with other pathways including oxidative stress, hypertension, or the renin angiotensin-aldosterone system, and promotes progressive kidney injury likely via fibrogenesis, phenotypic differentiation or cell death." (PMID 38965604, 2024). "Existing studies have identified several risk factors in the development of diabetic nephropathy, including endothelial dysfunction, smoking, stimulation of the renin-angiotensin system, obesity, and hypertension." (PMID 38809295, 2024).